CXCL12 (C-X-C motif chemokine ligand 12)
Diseases named in the same sentence as CXCL12 in open-access papers (continued):
Sharing a sentence is not in itself a finding about the gene and the disease.
tumor (continued). "PSCs produce NF-kB, which increases CXCL12 secretion, thereby reducing cytotoxic T lymphocyte infiltration, promoting pancreatic cancer cell survival and tumor growth." (PMID 40136652, 2025). "Previous studies highlight the critical role of MIF and its interactions with chemokine receptors CXCR7 and CXCL12 in tumor growth, prognosis, and treatment of prostate cancer." (PMID 41159021, 2025). "The CXCL12 concentration gradient then drives the extravasation of CXCR4-positive tumor cells in circulation, leading to organ-specific metastasis." (PMID 40075611, 2025). "CXCL12 can further polarize macrophages towards the M2 type, suppressing the anti‐tumor immune response and promoting tumor growth." (PMID 40145607, 2025). "Studies have shown that CXCL12-enriched zones can sequester effector T cells away from tumor nests, limiting cytotoxic responses." (PMID 40607416, 2025). "These experiences underscore the need for biomarker-gated eligibility, combination designs (e.g., CXCR4 blockade to disrupt CXCL12-mediated exclusion), and careful on-target/off-tumor safety monitoring when engaging broadly expressed stromal markers." (PMID 40940809, 2025). "Our results showed that primary tumor-derived exosomes loaded with HIF-2A recruited M2 macrophages by enhancing CXCL12 secretion from peritumoral fibroblasts and promoting tumor invasion." (PMID 40756343, 2025). "The CXCR4/CXCL12 axis, for example, has been shown to regulate neutrophil-tumor cell interactions, promoting neutrophil infiltration into tumors and enhancing their pro-angiogenic activities." (PMID 40050933, 2025). "Breast cancer and stromal cells in TME cells secrete chemokines CCL2, CCL5 (RANTES), CCL20, CCL22, and CXCL12 which, by binding to the corresponding receptors, induce Treg homing to tumor tissue." (PMID 40940764, 2025). "This reveals that NQO1 activates the NF‐κB signaling pathway by reducing the ubiquitination of p65, which subsequently upregulates CXCL12 and promotes tumor progression." (PMID 41028931, 2025). "For instance, human tumor microenvironments exhibit elevated expression of CXCL12 (CXCR4 ligand) and CCL20 (CCR6 ligand), creating a chemokine gradient that potentiates Th17 cell infiltration into tumors." (PMID 41296387, 2025). "During tumor development, tumor cells with high CXCR4 expression can spread or metastasize to tissues or organs with high CXCL12 expression through chemotaxis." (PMID 41413548, 2025). "The CXCL12/CXCR4 axis plays a multifaceted role in tumor progression through interactions with stromal and immune components." (PMID 40607416, 2025). "Upon binding CXCR4, CXCL12 promotes multiple downstream signalling cascades that can facilitate tumour survival/progression and even resistance." (PMID 41002447, 2025). "Recent studies have shown that inhibiting CXCR4 or CXCL12 can enhance tumor immunity by promoting CD8+ T-cell retention." (PMID 40141028, 2025). "The overexpression of the CXCR4/CXCL12 axis induces metastasis formation in different ways: in the tumor microenvironment (TME), hypoxia and toxins cause an increase in CXCL12 levels, generating the migration of CXCR4-expressing tumor cells." (PMID 40142155, 2025). "We found that exosomes containing HIF2A-mRNA released from primary tumor cells stimulate CXCL12 secretion in peritumor fibroblasts, which recruits M2 macrophages to peritumor tissues and promotes tumor invasion." (PMID 40756343, 2025). "When CXCL12 activates its receptor, angiogenesis, tumor cell survival, proliferation, and chemoresistance are promoted." (PMID 40142155, 2025). "Aberrant expression of CXCL12/CXCR4 has been observed in diverse tumor types, and are believed to act as a crucial chemokine-chemokine receptor in promoting tumor growth.CXCL12 and CXCR4 have direct or indirect effects on tumor development." (PMID 40166682, 2025). "The dysregulation of hsa-miR-135b, leading to altered CXCL12 expression, can significantly affect tumor behavior." (PMID 40426863, 2025).
tumor (continued). "Various CXC chemokine receptors are upregulated in HCC tumor cells, with CXCL2 and CXCL8 released by tumor-associated monocytes and with CXCL12 released by cancer-associated fibroblasts (CAFs) and stromal cells." (PMID 40721870, 2025). "The anti-metastatic effects of Plerixafor reported in TNBC preclinical models were due in part to inhibition of tumour cell homing to the CXCL12-rich environments, such as the bone marrow and lungs." (PMID 41002447, 2025). "The CXCL12/CXCR4 axis is also involved in tumor growth, tumor cell-microenvironment interactions, vasculogenesis and angiogenesis." (PMID 39035006, 2024). "Monocytes secrete chemokines, including CXCL12, during tumour progression, which further promotes the transition from M1 macrophages to M2 macrophages, ultimately supporting the tumour, inducing angiogenesis, and promoting immunosuppression." (PMID 38393307, 2024). "CAFs also produce stromal cell-derived factor 1 (SDF-1 or CXCL12), which is involved in both the recruitment of endothelial progenitors to the tumor and in cancer cell growth." (PMID 39765634, 2024). "In PDAC, CAF-secreted CXCL12 contributed to tumor progression and gemcitabine resistance via upregulating SATB-1 secretion." (PMID 38540204, 2024). "CXCL12, also known as stromal cell-derived factor 1 (SDF-1), has been shown to enhance tumor growth and angiogenesis through the CXCL12/CXCR4 pathway." (PMID 38602594, 2024). "One study found that CXCL12 expression in the bone marrow in a lung cancer model provided a displacement signal for CXCR4 tumor cells, increasing their invasion of the environment." (PMID 38770000, 2024). "In malignancies, the chemotactic and homeostatic functions of CXCL12 support tumor progression and invasion." (PMID 39409924, 2024). "The C-X-C chemokine receptor type 4/C-X-C motif chemokine 12 (CXCR4/CXCL12) interaction plays an important role in orchestrating tumor cells and CAFs." (PMID 38587644, 2024). "The high CXCR4 expression in the TNBC primary xenograft tumors, but not in the cell culture, caused us to ask if the CXCR4 stromal-expressed ligand, CXCL12, was responsible for the MDMX-associated upregulation of CXCR4 in the tumor." (PMID 39766093, 2024). "We underlined the value of CAFs in regulating tumor-promotion functions of myeloid cells through the production of MIF, CSF1, CXCL12, and FN1." (PMID 39323622, 2024). "Mechanistic insights reveal that tumor-infiltrating Tc17 cells induce tumor cells to produce CXCL12, promoting the migration of MDSCs to the TME in a CXCR4-dependent manner." (PMID 39906741, 2024). "Bidirectional crosstalk between tumor cells and CAFs enhances the ability of fibroblasts to secrete various pro-tumor chemokines, including CXCL12/CXCR4 axis, CCL2, CCL5, CCL7, CXCL8, and CXCL14." (PMID 39092186, 2024). "Gene abundance comparison between the MIF and CXCL pathways revealed significantly higher MIF expression in tumor cells than CXCL12 expression in CD3+αβT cells." (PMID 38386050, 2024). "CXCL12 is a stromal cell-derived chemokine, playing diverse roles in cellular functions including tumor growth and metastasis." (PMID 39759028, 2024). "Chen et al44 established a sustainable primary culture that highlighted the function of CAFs in tumor cell proliferation, particularly through the secretion of chemokines and growth factors such as CXCL12 and HGF." (PMID 39834587, 2024). "Our findings demonstrated that the expression of CXCL12 in cHCC–CCA tumor cells was positively correlated with the intratumoural TLS score and TLS maturation." (PMID 38767772, 2024). "Due to tumor immune tolerance and the heterogeneity of the tumor microenvironment, several preclinical risks need to be addressed for the application of CXCL12 treatment and CXCR4+ B cell adoptive transfer." (PMID 39422063, 2024). "The authors also mentioned the relationship between CXCR4 and CXCL12 as a potential new target to prevent tumor angiogenesis in PCa." (PMID 38745115, 2024).
tumor (continued). "CAFs derived from ASCs secrete factors like IL-6, CXCL12, and Wnt proteins that maintain the stemness of cancer cells and promote tumor-initiating potential." (PMID 39519109, 2024). "C-X-C chemokine receptor type 4 (CXCR4), expressed on cancer cells, binds to CXCL12 and promotes tumor growth." (PMID 39404428, 2024). "CXCL12 recruits regulatory B cells into the tumor which can exacerbate tumor progression via IL-10 and TGF-β expression." (PMID 38726320, 2024). "These TAMs are attracted into blood vessels by CXCL12+ fibroblasts surrounding the blood vessels and differentiate into perivascular macrophages, which facilitate tumor metastasis and assist the migration of cancer cells into the bloodstream." (PMID 39606239, 2024). "Emerging studies suggest the role of CXCL12 in multifaceted function in MM, including tumor migration and chemoresistance." (PMID 38475811, 2024). "In a xenograft murine model, SPI1/CXCL12 was associated with increased tumor weights when SPI1 was present, while CXCL12 knockdown led to decreased tumor weights." (PMID 39409924, 2024). "In the exosome cohort CXCL12 expression was strongly correlated with EGFR status, CD44v6 was associated with tumor stage, TTF-1 expression & chromogranin protein expression and HIF1A & TGFBR2 showed positive correlation with CEA expression & CK20 expression." (PMID 38877052, 2024). "Currently, there are many tumor environments in which CXCR4-positive cancer cells are highly likely to spread to tissues that express SDF1 (CXCL12), such as the bone marrow." (PMID 39154307, 2024). "This hydrogel serves as a carrier for the local delivery of doxorubicin liposomes (Dox Lipo) to improve lung cancer treatment in vivo, employing CXCL12 as a chemoattractant to effectively capture and engage tumor cells." (PMID 39771496, 2024). "Neutrophils and macrophages can be recruited by CAF-derived CXCL12, while T cells can be excluded from the tumor in a CXCL12-dependent manner." (PMID 38254801, 2024). "This induction of CXCL12 contributes to the acquisition of cancer-associated fibroblast (CAF) characteristics, ultimately promoting tumor growth and metastasis." (PMID 38920657, 2024). "C-X-C motif chemokine ligand 12 (CXCL12; Stromal Cell-Derived Factor 1 [SDF-1]), most notably known for its role in embryogenesis and hematopoiesis, has been implicated in tumor pathophysiology and neovascularization." (PMID 39698751, 2024). "In breast cancer, tumor-secreted SPP1 induces fibroblasts to differentiate into myofibroblasts, which subsequently facilitate epithelial-mesenchymal transition (EMT) and the metastasis of tumor cells through the secretion of CXCL12." (PMID 39529085, 2024). "Tranilast inhibits the migration of M2 macrophages by suppressing CXCL12 secretion by CAFs, while also inhibiting tumor growth, fibrosis, and the infiltration of M2 macrophages and mast cells." (PMID 39534084, 2024). "Previous studies on CXCR4/CXCL12 signaling demonstrated that the interplay between CAFs and tumor cells played a critical role in tumor progression." (PMID 38587644, 2024). "A multitude of studies have demonstrated that CXCL12 fosters tumor growth and metastasis, and pharmacological interventions targeting the STAT3 pathway have proven efficacious for various cancers." (PMID 38920657, 2024). "Meanwhile, Cxcl10 has inhibitory effect on tumor progression, Cxcl12, Cxcl14, Ppbp, Pf4 and Ccl8 play an important role in promoting tumor progression." (PMID 38622609, 2024). "An interesting mechanism proposed recently suggests CXCL12 provides tumor control via T cell retention in tumors." (PMID 38786066, 2024). "CXCL12 influences tumor progression through interactions with its 2 receptors, CXCR4 and ACKR3, especially CXCR4." (PMID 39545420, 2024). "A variety of tumor cell types release osteopenia and CXCL12/SDF-1 which mobilize stem cells from the bone marrow and facilitate their contribution to the formation of blood vessels within the tumor and promoting tumor growth." (PMID 38715921, 2024).
tumor (continued). "Under hypoxic conditions, CXCL12 mediated the mobilization of endothelial progenitor cells toward vascular endothelial cells, thereby promoting tumor angiogenesis." (PMID 38716256, 2024). "Some studies have reported that CAFs can secrete CXCL12, which plays an important role in tumour progression." (PMID 38766687, 2024). "Tumor-associated pDCs (TA-pDCs; i.e. into the tumor milieu or tumor-draining lymph nodes) are recruited at the tumor site by chemokines (e.g. CXCL12 and CCL20) released by cancer cells or by the TME." (PMID 39020402, 2024). "CLL cells and tumor-associated stromal cells also produce and secrete FGF-2, TNF-α, CXCL-12, CXCL-2, NGAL, IGF-1, progranulin, and angiogenin." (PMID 39796700, 2024). "Twist1 is also known to transcript CCL2 and CXCL12 that can recruit pro-tumor myeloid cells, serving as a potentially additional mechanism to induce vascular niche-mediated Mφ immunosuppression." (PMID 38416830, 2024). "The CXCR4—CXCL12 axis regulates the transmission of diverse downstream signaling pathways crucial for tumor cell survival, proliferation, and migration, and PD-1/PD-L1 controls immune tolerance." (PMID 38727318, 2024). "CCL5, CXCL1, CXCL2, CXCL5, and CXCL12 are chemokines produced by senescent cells that have opposite effects on tumor development." (PMID 39007138, 2024). "The recruitment of TAMs by CXCL12 is being investigated as a mechanism driving tumor proliferation and invasion." (PMID 39409924, 2024). "More interestingly, CAFs are capable of secreting chemokine C-X-C motif ligand 12 (CXCL12) to elevate the expression levels of anti-apoptotic proteins Bcl-2 and Survivin in the tumor cells, leading to the occurrence of drug resistance." (PMID 38322116, 2024). "TAMs are usually dependent on chemokines such as CCL2, CCL5 and CXCL12 for recruitment from peripheral monocytes/macrophages into the TME at the primary tumor site." (PMID 39135069, 2024). "In turn, various cells, such as CAFs and TAM in TME can also secrete factors, such as cytokines, vascular endothelial growth factor (VEGF), CXCL12, and interleukins to accelerate tumor angiogenesis." (PMID 39033180, 2024). "A study comparing primary tumors derived from MDA-MB-231 xenograft mice to MDA-MB-231 parental cells grown in a cell culture showed that, with exogenous CXCL12, the primary tumor cells expressed more CXCR4 and activated PI3K/AKT signaling." (PMID 39766093, 2024). "The CXCL12/CXCR4 pathway is believed to not only modulate the biological behaviors of tumor cells but also orchestrate the metastatic dissemination of CXCR4-positive tumor cells toward organs or tissues that express CXCL12." (PMID 39281319, 2024). "Direct interactions between CAFs, tumour cells and immune cells cause this immunosuppressive environment by excretion of hepatocyte growth factors (HGF), chemokines such as C-X-C motif chemokine 12 (CXCL12), exosomes and ECM proteins." (PMID 39851940, 2024). "Adhesion molecules are important in CLL pathogenesis as they allow direct interaction between leukemic cells and TME, or indirectly induce cytokine release, including CXCL12, that promotes tumor growth, migration, homing, and survival." (PMID 39198407, 2024). "They found that the CXCL12 and CCL21 ligands and their corresponding receptors, CXCR4 and CCR7, were highly and significantly expressed in tumor cells with lymph node metastases associated with shorter survival in this cohort." (PMID 39001456, 2024). "In fact, CAFs are believed to recruit EPCs to BC TME via the secretion of massive amounts of CXCL-12, which interact with CXCR4 on EPCs, promoting tumor angiogenesis after differentiation into tumor-associated vascular endothelial cells (TAVECs)." (PMID 39609700, 2024). "Dysregulation of CXCL12 secretion by tumor cells and expression of CXCR4 by immunosuppressive cells induces the creation of an inhibitory TME by fostering the infiltration of the mentioned regulatory and cancer-associated cells." (PMID 39070795, 2024).